CAMSAP2 (calmodulin regulated spectrin associated protein family member 2)
Description:
Key microtubule-organizing protein that specifically binds the minus-end of non-centrosomal microtubules and regulates their dynamics and organization. Specifically recognizes growing microtubule minus-ends and autonomously decorates and stabilizes microtubule lattice formed by microtubule minus-end polymerization. Acts on free microtubule minus-ends that are not capped by microtubule-nucleating proteins or other factors and protects microtubule minus-ends from depolymerization. In addition, it also reduces the velocity of microtubule polymerization. Through the microtubule cytoskeleton, also regulates the organization of cellular organelles including the Golgi and the early endosomes. Essential for the tethering, but not for nucleation of non-centrosomal microtubules at the Golgi: together with Golgi-associated proteins AKAP9 and PDE4DIP, required to tether non-centrosomal minus-end microtubules to the Golgi, an important step for polarized cell movement. Also acts as a regulator of neuronal polarity and development: localizes to non-centrosomal microtubule minus-ends in neurons and stabilizes non-centrosomal microtubules, which is required for neuronal polarity, axon specification and dendritic branch formation. Through the microtubule cytoskeleton, regulates the autophagosome transport.
Synonyms: CAMSAP1L1; KIAA1078
Tractability: PROTAC: ubiquitination databases record sites on it; its protein half-life has been measured.
Gene: Protein-coding gene on chromosome 1 (200,738,893 to 200,860,707, forward strand). Ensembl gene ENSG00000118200.
Subcellular location: Cytoplasm, cytoskeleton; Golgi apparatus; Cytoplasm, cytoskeleton, cilium basal body; Cytoplasm
Subcellular location (Human Protein Atlas): Microtubule ends; Basal body; Cytosol; Golgi apparatus; Primary cilium
Gene Ontology:
Molecular function: microtubule minus-end binding; protein binding; calmodulin binding; microtubule binding; spectrin binding
Biological process: axon development; microtubule cytoskeleton organization; regulation of dendrite development; regulation of Golgi organization; regulation of microtubule polymerization; regulation of organelle organization; cytoplasmic microtubule organization; negative regulation of microtubule depolymerization; neuron projection development
Cellular component: centrosome; Golgi apparatus; microtubule end; microtubule minus-end; ciliary basal body; cytoplasm; cytoskeleton; microtubule cytoskeleton
Genetic constraint (gnomAD): Loss-of-function variants: 14 observed, 111.76 expected, observed/expected ratio (o/e) 0.13, 90% interval 0.082 to 0.2. The synonymous counts are far from expectation, so gnomAD's model fits this gene poorly and the ratio says little. Missense variants: 1,166 observed, 1,576.2 expected, observed/expected ratio (o/e) 0.74, 90% interval 0.7 to 0.78. Synonymous variants: 441 observed, 538.93 expected, observed/expected ratio (o/e) 0.82, 90% interval 0.76 to 0.88.
Homologues: Orthologues: macaque CAMSAP2 (99% identical), chimpanzee CAMSAP2 (99% identical), dog CAMSAP2 (96% identical), rabbit CAMSAP2 (95% identical), rat Camsap2 (92% identical), mouse Camsap2 (92% identical), guinea pig CAMSAP2 (91% identical), pig CAMSAP2 (84% identical), tropical clawed frog camsap2 (69% identical), zebrafish camsap2a (58% identical), Drosophila melanogaster Patronin (24% identical), Caenorhabditis elegans ptrn-1 (20% identical). Paralogues in human: CAMSAP1 (42% identical), CAMSAP3 (35% identical).
Diseases named in the same sentence as CAMSAP2 in open-access papers:
CAMSAP2 is named in the same sentence as 21 diseases in open-access papers, as found by Europe PMC text mining. Sharing a sentence is not in itself a finding about the gene and the disease. The quoted sentences say what the papers report.
hepatocellular carcinoma (4 papers, 2020 to 2025). A malignant tumor that arises from hepatocytes. "CAMSAP2 has been reported to act as an oncogene in hepatocellular carcinoma." (PMID 36207462, 2022). "The effects of CASMAP2 KD on EB1 amounts on microtubules appear variable depending on cell types, as CAMSAP2 KD caused upregulation of EB1 on microtubules in HeLa cells, but downregulation in hepatocellular carcinoma, or no changes in rat Sertoli cells." (PMID 39787108, 2025). "For example, CAMSAP2 promotes hepatocellular carcinoma metastasis by promoting non-centrosomal microtubule acetylation." (PMID 41464116, 2025).
colorectal cancer (2 papers, 2022 to 2025). A primary or metastatic malignant neoplasm that affects the colon or rectum. "Taken together, these data demonstrated that CAMSAP2 transcriptionally upregulated MMP-1 in colorectal cancer cells." (PMID 36207462, 2022). "The number of tumor cells invaded through the matrigel-coated transwell inserts was increased by CAMSAP2 in all tested colorectal cancer cells." (PMID 36207462, 2022). "Taken together, these data confirmed that knockdown of CAMSAP2 hampered the metastatic ability of colorectal cancer." (PMID 36207462, 2022). "In this study, we detected the expression and investigated the potential role and molecular mechanism of CAMSAP2 in colorectal cancer." (PMID 36207462, 2022). "The results showed that the mRNA and protein levels of CAMSAP2 in two tested colorectal cancer cells were much higher in colorectal cancer cells transfected with CAMSAP2-expressing plasmids compared with those cells transfected with empty vector." (PMID 36207462, 2022). "The results showed that the migration and invasion induced by CAMSAP2 overexpression was inhibited by SP600125 in both tested colorectal cancer cells." (PMID 36207462, 2022). "We also performed transwell migration assay to determine the role of CAMSAP2 in colorectal cancer cell migration." (PMID 36207462, 2022). "In this study, qRT-PCR and immunoblotting analysis were used to detect the mRNA and protein levels of CAMSAP2 in colorectal cancer tissues and cell lines." (PMID 36207462, 2022). "To investigate the expression of CAMSAP2 in colorectal cancer, we first analyzed two independent microarray datasets downloaded from GEO." (PMID 36207462, 2022). "By gain- and loss-of function experiments, we demonstrated that MMP-1 was a substantial downstream target of CAMSAP2, and it played a crucial role in regulating the migration and invasion induced by CAMSAP2 in colorectal cancer cells." (PMID 36207462, 2022). "Vice versa, knocking down CAMSAP2 by lentivirual shRNAs reduced the mRNA levels of MMP-1 in both tested colorectal cancer cells." (PMID 36207462, 2022). "The results showed that overexpression of CAMSAP2 upregulated the wound healing rate in all tested colorectal cancer cells, compared to the control group." (PMID 36207462, 2022). "Consistently, Western blot analysis also revealed that CAMSAP2 was highly expressed in all three tested colorectal cancer cell lines, compared to the FHC cells." (PMID 36207462, 2022). "The results showed that the mRNA level of CAMSAP2 was much higher in colorectal cancer cells then that in the human normal colorectal FHC cells." (PMID 36207462, 2022). "Taken together, these findings demonstrated that CAMSAP2 promoted colorectal cancer metastasis in vivo." (PMID 36207462, 2022). "We then detected the expression of CAMSAP2 in 76 paired colorectal cancer tissues and adjacent tissues by using qRT-PCR." (PMID 36207462, 2022). "The results showed that overexpression or knockdown of CAMSAP2 hardly affected the number and size of colony formed in soft agar in both tested colorectal cancer cells." (PMID 36207462, 2022). "Ectopic expression of CAMSAP2 significantly enhanced the migration, invasion and metastasis of colorectal cancer cells." (PMID 36207462, 2022). "The level of CAMSAP2 in colorectal cancer tissues was much higher than that in the corresponding normal tissues." (PMID 36207462, 2022). "In this study, we discovered that the expression of CAMSAP2 was highly elevated in colorectal cancer tissues and cell lines." (PMID 36207462, 2022). "The results revealed that CAMSAP2 is highly expressed in colorectal cancer cells and clinical samples." (PMID 36207462, 2022). "Subsequently, we examined CAMSAP2 expression in colorectal cancer cell lines using qRT-PCR." (PMID 36207462, 2022). "Subsequently, we performed transwell assay to test whether targeting JNK hampered CAMSAP2-mediated migration and invasion in colorectal cancer cells." (PMID 36207462, 2022).
colorectal cancer (continued). "In addition, Kaplan–Meier survival analysis also revealed that a higher expression of CAMSAP2 corrected with reduced overall survival in colorectal cancer patients (P < 0.001)." (PMID 36207462, 2022). "The results showed that CAMSAP2 was highly elevated in colorectal cancer tissues and cell lines." (PMID 36207462, 2022). "Subsequently, we determined whether CAMSAP2 promotes colorectal cancer cell growth by using MTT assay." (PMID 36207462, 2022). "Moreover, the high CAMSAP2 expression was positively correlated with tumor invasion depth, lymph node metastasis, distant metastasis, and the poor prognosis of colorectal cancer." (PMID 36207462, 2022). "Subsequently, we tested whether silencing CAMSAP2 decreases the invasive ability of colorectal cancer cell using transwell invasion assay." (PMID 36207462, 2022). "Furthermore, we also performed soft agar colony formation assay to determine the effect of CAMSAP2 on the growth of colorectal cancer cells." (PMID 36207462, 2022). "In addition, the result of Kaplan–Meier survival analysis indicated that patients with high CAMSAP2 expression had a poor prognosis in colorectal cancer patients derived from two independent microarray datasets downloaded from GEO." (PMID 36207462, 2022). "Next, we performed wound healing assay to investigate whether overexperesson of MMP-1 reduces the inhibitory effects of CAMSAP2 shRNAs on colorectal cancer cell migration." (PMID 36207462, 2022). "Next, we performed wound healing assay to detect whether CAMSAP2 promotes colorectal cancer cell migration." (PMID 36207462, 2022). "Additionally, ectopic expression of CAMSAP2 in colorectal cancer cells promoted the migration and invasion in vitro and enhanced the lung metastasis in nude mice." (PMID 36207462, 2022). "Additionally, upon treatment with SP600125, the promoter activity of MMP-1 induced by CAMSAP2 upregualtion was inhibited in both tested cell lines of colorectal cancer." (PMID 36207462, 2022). "In addition, transwell migration and invasion assays also showed that silencing MMP-1 inhibited the migration and invasion induced by CAMSAP2 in both tested colorectal cancer cells." (PMID 36207462, 2022). "Next, we asked how CAMSAP2 regulates MMP-1 in colorectal cancer cells." (PMID 36207462, 2022). "Next, we examined whether knockdown of CAMSAP2 inhibits colorectal cancer cell migration using wound healing assay." (PMID 36207462, 2022). "In summary, our study revealed that CAMSAP2 promoted the migration, invasion and metastasis of colorectal cancer cells through activation of JNK/c-Jun/MMP-1 signaling pathway, suggesting CAMSAP2 is a potential therapeutic target for metastatic colorectal cancer." (PMID 36207462, 2022). "Taken together, our findings demonstrated that CAMSAP2 promoted colorectal cancer cell migration, invasion and metastasis through activation of JNK/c-Jun/MMP-1 signaling pathway, indicating CAMSAP2 is a promising therapeutic target for the treatment of metastatic colorectal cancer patients." (PMID 36207462, 2022). "Wound-healing, transwell migration and invasion assay were performed to determine whether CAMSAP2 promotes the capabilities of migration and invasion of colorectal cancer cells." (PMID 36207462, 2022). "However, the expression of CAMSAP2 and its functions in colorectal cancer cell migration and invasion remains unclear." (PMID 36207462, 2022). "Moreover, a similar phenomenon was observed in CAMSAP2-depleted colorectal cancer cells." (PMID 36207462, 2022). "Therefore, we hypothesized that CAMSAP2 may regulate MMP-1 transcription in colorectal cancer cells by stimulating JNK/c-Jun signaling pathway." (PMID 36207462, 2022). "Taken together, our results confirmed that CAMSAP2 enhanced the expression of MMP-1 through activation of JNK/c-Jun signaling pathway, and thereby promoted the migration and invasion of colorectal cancer cells." (PMID 36207462, 2022).
colorectal cancer (continued). "However, the expression CAMSAP2 and its potential roles in colorectal cancer remain unclear." (PMID 36207462, 2022). "The expression of CAMSAP2 mRNA was elevated in colorectal cancer, compared to the normal para-cancerous tissues." (PMID 36207462, 2022). "Collectively, these findings indicated that CAMSAP2 did not affect colorectal cancer cell growth." (PMID 36207462, 2022).
liver cancer (2 papers, 2020 to 2022). An epithelial or non-epithelial malignant neoplasm that arises from the liver. "Immunohistochemistry (IHC) tissue microarray data from Human Protein Atlas program database revealed high or medium CAMSAP2 staining intensity in 10 out of 12 liver cancer samples, whereas only 3 out of 12 cases showed medium staining of CAMSAP1 and CAMSAP3." (PMID 32206120, 2020). "Kaplan-Meier analysis based on TCGA data revealed that liver cancer patients with high CAMSAP2 mRNA levels had a significantly shorter overall survival (OS) and disease-free survival (DFS) than those who with low CAMSAP2 mRNA levels." (PMID 32206120, 2020).
Alzheimer disease (1 paper, 2024). A progressive, neurodegenerative disease characterized by loss of function and death of nerve cells in several areas of the brain leading to loss of cognitive function such as memory and language. "Interestingly, several transcriptome-wide significant and colocalized genes outside genome-wide significant GWAS loci point to biologically relevant pathways related to neurodevelopment and neurodegeneration (PICALM, a known Alzheimer disease gene, CAMSAP2, AGTPBP1, SETD1A, EPRS, PADI2 and PSAP)." (PMID 38811690, 2024).
colon adenocarcinoma (1 paper, 2020). "Moreover, the increased mRNA expression of CAMSAP2 also observed in pancreatic adenocarcinoma (PAAD), stomach adenocarcinoma (STAD) and colon adenocarcinoma (COAD) tissues based on TCGA data." (PMID 32206120, 2020).
COVID-19 (1 paper, 2022). A disease caused by infection with severe acute respiratory syndrome coronavirus 2. "The potential mechanism of action of HXZQ for COVID-19 is inhibiting SARS-CoV-2 replication, improving immune, and anti-inflammatory, mainly by acting on 3CLpro, PTGS2, AR, HSP90AB1, CAMSAP2, PPARG, NOS2, and other targets." (PMID 36388945, 2022).
metastatic colorectal cancer (1 paper, 2022). "Our findings indicate that CAMSAP2 is a promising therapeutic target for patients with metastatic colorectal cancer." (PMID 36207462, 2022).
tumor (5 papers, 2020 to 2025). "Analysis of patient samples and public datasets revealed that CAMSAP2 is highly expressed in GC tissues and is associated with advanced tumor stage, higher grade, and elevated levels of serum markers such as CEA and CA19-9." (PMID 41244835, 2025). "The expression of CAMSAP2 was positively associated with tumor invasion depth (P = 0.0099), lymph node metastasis (P = 0.0359), distant metastasis (P = 0.0042) and TNM stage (P = 0.0249)." (PMID 36207462, 2022). "Analysis of the clinicopathological characteristics revealed that CAMSAP2 overexpression was strongly associated with multiple tumors, increased tumor size, microvascular invasion, poor tumor differentiation, and a higher tumor-nodule-metastasis stage." (PMID 32206120, 2020). "The results of qRT-PCR assay showed that the mRNA level of CAMSAP2 in both tested tumor cells was five times lower in response to CAMSAP2 lentivirual shRNAs than those cells transduced with shNC." (PMID 36207462, 2022). "We found elevated expression of circSOD2 and CAMSAP2 while reduced expression of miR-2355-5p in NSCLC tumor tissues." (PMID 35188072, 2022). "Our results revealed that HDAC6, a promising target for cancer therapy, was inversely downregulated in HCC and uniquely endowed with tumor-suppressive activity by regulation CAMSAP2-mediated microtubule acetylation." (PMID 32206120, 2020). "CAMSAP2 is a significant promoter of tumor progression in GC." (PMID 41244835, 2025). "Moreover, transwell migration assay also revealed that ectopic expression of CAMSAP2 promoted the number of tumor cells migrated through the membrane." (PMID 36207462, 2022). "The functions of this family members in tumors show significant heterogeneity, with CAMSAP1 and CAMSAP2 mainly exerting pro-tumorigenic effects, while CAMSAP3 exhibits tumor suppressor properties." (PMID 41464116, 2025).
cancer (2 papers, 2020 to 2022). A tumor composed of atypical neoplastic, often pleomorphic cells that invade other tissues. "Taken together, these findings from us and others suggested that JNK/c-Jun signaling pathway plays an important role in CAMSAP2-induced metastasis in various malignant tumors." (PMID 36207462, 2022). "IHC staining confirmed that CAMSAP2 was upregulated in PAAD, STAD and COAD cancer specimens." (PMID 32206120, 2020).
CAMSAP2 also shares sentences with these, for which no sentence is quoted: epilepsy (4 papers); deafness (1); endothelial dysfunction (1); Epileptic encephalopathy (1); fibrosarcoma (1); hemorrhage (1); leukoplakia (1); lymph node metastasis (1); non-small cell lung carcinoma (1); pancreatic adenocarcinoma (1); small cell lung carcinoma (1); stomach adenocarcinoma (1).